MELTF (melanotransferrin)
Description:
Involved in iron cellular uptake. Seems to be internalized and then recycled back to the cell membrane. Binds a single atom of iron per subunit. Could also bind zinc.
Synonyms: CD228; MAP97; MFI2; FLJ38863; MGC4856; MTF1; MTf
Tractability: Antibody: its Gene Ontology location is reachable by antibodies, with high confidence; UniProt places it where antibodies can reach, with medium confidence; UniProt predicts a signal peptide or a membrane-spanning region.
Gene: Protein-coding gene on chromosome 3 (196,980,590 to 197,029,874, reverse strand). Ensembl gene ENSG00000163975.
Subcellular location: Cell membrane (Isoform 1)
Pathways (Reactome):
Metabolism of proteins: Post-translational modification: synthesis of GPI-anchored proteins; Post-translational protein phosphorylation; Regulation of Insulin-like Growth Factor (IGF) transport and uptake by Insulin-like Growth Factor Binding Proteins (IGFBPs)
Gene Ontology:
Molecular function: iron ion binding; protein binding
Biological process: iron ion transport; negative regulation of substrate adhesion-dependent cell spreading; positive regulation of extracellular matrix disassembly; positive regulation of plasminogen activation; regulation of cell growth; regulation of cell population proliferation
Cellular component: cell surface; extracellular exosome; plasma membrane; early endosome; endoplasmic reticulum lumen; extracellular region; recycling endosome
Genetic constraint (gnomAD): Loss-of-function variants: 67 observed, 79.04 expected, observed/expected ratio (o/e) 0.85, 90% interval 0.69 to 1.04. The upper end of that interval is the gene's LOEUF score, 1.04, which puts it in group 4 of 6, group 1 being the genes least tolerant of losing a copy. Missense variants: 987 observed, 1,011.2 expected, observed/expected ratio (o/e) 0.98, 90% interval 0.93 to 1.03. Synonymous variants: 456 observed, 432.8 expected, observed/expected ratio (o/e) 1.05, 90% interval 0.98 to 1.14.
Homologues: Orthologues: chimpanzee MELTF (99% identical), macaque MELTF (93% identical), pig MELTF (90% identical), dog MELTF (84% identical), rat Meltf (84% identical), mouse Meltf (84% identical), rabbit MELTF (78% identical), guinea pig MELTF (70% identical), tropical clawed frog meltf (54% identical), zebrafish meltf (47% identical). Paralogues in human: LTF (39% identical), TF (39% identical), SRPRB (4% identical).
Diseases named in the same sentence as MELTF in open-access papers:
MELTF is named in the same sentence as 28 diseases in open-access papers, as found by Europe PMC text mining. Sharing a sentence is not in itself a finding about the gene and the disease. The quoted sentences say what the papers report.
melanoma (19 papers, 2010 to 2025). A malignant, usually aggressive tumor composed of atypical, neoplastic melanocytes. "The expression of MELTF, which encodes the protein melanotransferrin, increases in several cancers, including lung adenocarcinoma, ovarian cancer, and melanoma." (PMID 39672307, 2024). "Melanotransferrin (p97) is a GPI-anchored protein expressed in melanomas very similar to Tf that instead of Tf receptor, are transported through the endothelium by low-density lipoprotein-receptor related protein (LRP)." (PMID 40944840, 2025). "Accordingly, the MELTF gene codes for one of the first melanoma tumor antigens identified, and it is involved in multiple steps of tumor cellular transformation." (PMID 39940906, 2025). "MELTF (also known as CD228) is a membrane-bound transferrin, first associated with melanoma development." (PMID 38168272, 2023). "Melanotransferrin (CD228), firstly reported as a melanoma-associated antigen, is a membrane-bound glycoprotein of an iron-binding transferrin homolog." (PMID 33746574, 2021). "A soluble form of melanotransferrin characterized to have low efficiency in delivering iron was found to foster melanoma cell migration, invasion, and endothelial cell angiogenesis." (PMID 33287315, 2020). "As recently reviewed 42, the role of melanotransferrin is still elusive despite its implication in malignant melanoma." (PMID 26038108, 2015). "Melanotransferrin (MTf) is a surface protein found on melanoma cells." (PMID 40420216, 2025). "In melanoma, downregulation of MELTF inhibits tumor proliferation." (PMID 39672307, 2024). "Interestingly, despite a minor role in iron metabolism, gene silencing of melanotransferrin markedly reduced melanoma cell proliferation and tumor growth in mice." (PMID 33287315, 2020). "Similarly to TfR1, melanotransferrin is notably upregulated in melanoma tissues and, to a lesser degree, in liposarcoma and breast and lung cancers." (PMID 33287315, 2020). "Melanotransferrin has been identified as a surface molecule on melanoma cells." (PMID 23344048, 2013). "MELTF, also known as MTf (Melanotransferrin) or MTF1 (metal regulatory transcription factor 1), as an iron (Fe) binding transferrin homolog, is mainly expressed in melanoma and is low expression in normal tissues." (PMID 33287749, 2020). "Expression of melanotransferrin was found to correlate with increased transmigration of melanoma cells through the BBB, while blocking melanotransferrin significantly reduced transmigration." (PMID 23344048, 2013).
gastric cancer (5 papers, 2020 to 2025). A primary or metastatic malignant neoplasm involving the stomach. "Melanotransferrin (MELTF) is identified as a serological biomarker in gastric cancer, colorectal cancer, and lung cancer." (PMID 37583701, 2023). "Melanotransferrin (MELTF) was identified as a prognostic biomarker in gastric cancer, and the suppression of MELTF reduces the invasion ability of gastric cancer cells." (PMID 36185621, 2022). "Tissue and serum MELTF levels can be used as biomarkers of gastric cancer progression, and inhibition of MELTF expression can inhibit the invasive ability of gastric cancer cells." (PMID 34060213, 2021). "Level of melanotransferrin (MELTF) in tissue and sera serves as a prognostic marker of gastric cancer." (PMID 33414898, 2020). "Although its role in AML is yet to be elucidated, MELTF represents a known negative prognostic marker in colon and gastric cancers." (PMID 39940906, 2025).
Alzheimer disease (3 papers, 2018 to 2026). A progressive, neurodegenerative disease characterized by loss of function and death of nerve cells in several areas of the brain leading to loss of cognitive function such as memory and language. "Association of CSF Aβ, total tau (ttau), phosphorylated tau (ptau), and melanotransferrin (MTf) with cognitive scores in cognitively normal (CN), mild-cognitive impairment (MCI), or Alzheimer’s disease (AD)." (PMID 30906244, 2019). "Modeling the association of CSF Aβ, total tau (ttau), phosphorylated tau (ptau), and melanotransferrin (MTf) with neuroimaging measures of the hippocampus in cognitively normal (CN), mild cognitive impairment (MCI) or Alzheimer’s disease (AD)." (PMID 30906244, 2019). "Association of CSF Aβ, total tau (ttau), phosphorylated tau (ptau), and melanotransferrin (MTf) with hippocampal neuroimaging measures and cognitive scores in MCI non-converters (MCI-nc) and converters (MCI-c) to Alzheimer’s Disease." (PMID 30906244, 2019).
breast carcinoma (3 papers, 2016 to 2021). "Administration of melanotransferrin-trastuzumab conjugate (BT2111) reduced the number of HER2+ breast cancer metastases in the brain (by 68%) with tumours being 46% smaller in BT2111 treated mice relative to control mice." (PMID 34926242, 2021).
ovarian carcinoma (2 papers, 2023 to 2024). A malignant neoplasm originating from the surface ovarian epithelium. "In ovarian cancer, MELTF drives the epithelial to mesenchymal transition, leading to metastasis." (PMID 39672307, 2024). "Conversely, 8 genes showed increased expression in ovarian cancer tissues, including LCN2, CP, TFR2, LRP2, MELTF, LTF, SLC11A2, and STEAP3." (PMID 38186569, 2023).
bladder cancer (1 paper, 2020). "In the high-expressed group of MELTF, the enriched KEGG pathways were mainly focused on bladder cancer, proteasome, DNA replication, base excision repair, pyrimidine metabolism." (PMID 33287749, 2020).
brain tumours (1 paper, 2021). "We have previously shown that melanotransferrin (MTf; Uniprot P08582), a mammalian iron-transport protein, can deliver anti-cancer drugs that reduce the in situ growth of brain tumours." (PMID 33869275, 2021).
dementia (1 paper, 2022). Loss of intellectual abilities interfering with an individual's social and occupational functions. "Patients with dementia caused by AD also differ in serum melanotransferrin (p97) levels—melanotransferrin levels were elevated three to fourfold in AD compared to non-AD dementia and normal controls." (PMID 35911597, 2022).
glioblastoma multiforme (1 paper, 2016). "In another case the melanotransferrin antibody (MA) was conjugated with solid lipid nanoparticles (SLNs) to carry anticancer etoposide (ETP) across the BBB for managing glioblastoma multiforme (GBM)." (PMID 27056889, 2016).
leukemia (1 paper, 2025). A malignant (clonal) hematologic disorder, involving hematopoietic stem cells and characterized by the presence of primitive or atypical myeloid or lymphoid cells in the bone marrow and the blood.
Miscarriage (1 paper, 2025). A pregnancy that ends at a stage in which the fetus is incapable of surviving on its own, defined as the spontaneous loss of a fetus before the 22th week of pregnancy. "Both melanotransferrin (MELTF) and hemopexin (HPX) are involved in heme and iron metabolism with abnormal expression correlated with miscarriage." (PMID 40430124, 2025).
tumor (19 papers, 2010 to 2025). "Melanotransferrin (MFI2) is a newly identified tumor-associated protein, which consists of two forms of proteins, membrane-bound (mMFI2) and secretory (sMFI2)." (PMID 33127882, 2020). "Moreover, melanotransferrin overexpression is associated with high tumor grade and metastases in human colorectal cancer." (PMID 33287315, 2020). "As a member of the transferrin family, the transmembrane protein MFI2 (Melanotransferrin, also known as CD228) has gradually become a research hotspot due to its potential role in tumor metabolic reprogramming and metastatic microenvironment regulation." (PMID 40568599, 2025). "Among them, DKK1, LDHA and MELTF are high-expressed in tumor tissues compared with tissue adjacent to carcinoma, but GNG7 is low-expressed." (PMID 33287749, 2020). "In lung cancer, MELTF promotes tumor growth by stimulating the Notch pathway." (PMID 39672307, 2024). "Furthermore, PC3 prostate tumor-initiating cells with the molecular profile RIPOR2high/melanotransferrin (MFI2)low/LEF1low increased tumor angiogenesis." (PMID 35002526, 2022). "Melanotransferrin (MTF) is expressed in normal adult, fetal and tumour cells." (PMID 34441278, 2021). "Interestingly, of the few genes that, via sPLS-DA, were predicted to contribute to tumor regression at certain stage-to-stage interfaces—including DAPK2, PLAC9, ABCB9, MELTF, CTHRC1, and OCIAD2, testing for LUAD patient survivability via AK4 combination resulted in a negative prognosis." (PMID 34940617, 2021).
cancer (14 papers, 2010 to 2026). A tumor composed of atypical neoplastic, often pleomorphic cells that invade other tissues. "The expression of the cell proliferation promoter MELTF is higher in cancer compared to precancer and controls (p < 0.0001)." (PMID 39672307, 2024). "Melanotransferrin (MTf) is a surface-exposed and secreted protein of therapeutic interest in light of its use as a cancer target or as a drug-delivery system across the blood–brain barrier." (PMID 33436675, 2021). "We have previously shown that the soluble form of mammalian iron-binding protein melanotransferrin is able to deliver small anti-cancer agents to the brain and reduce the growth of tumors therein resulting in extending the survival of the treated animals." (PMID 34149342, 2021). "DACT1, VRK2, MELTF, and FGF12 have been implicated in cancers other than CC, and PRICKLE2 has been reported to correlate with CC." (PMID 32408396, 2020). "MFI2 (melanotransferrin) is a transferrin superfamily protein with a single high-affinity iron (III)-binding site that is required for cancer cell growth and proliferation." (PMID 21190562, 2010). "The increased stimulation of CCNE1 and MELTF by HPV16 could explain why individuals with HPV16-positive precancer are more likely to progress to cancer than individuals with HPV31-positive precancer." (PMID 39672307, 2024). "Our analysis showed increased CCNE1 and MELTF expression in cancer." (PMID 39672307, 2024). "Expression of innate immune system markers (APOBEC3A/B), DNA repair genes (BRCA1, BRCA2, PALB2, RAD51), cell cycle genes (CCNA2 and CCNE1), a cell proliferation gene (MELTF), and a T-cell regulator (Treg) marker (FOXP3) was elevated in cancer compared to precancer and controls." (PMID 39672307, 2024).
hematologic malignancies (1 paper, 2025). "Intriguingly, the consistent upregulation of MELTF in both AML and benzene exposure suggests its involvement in pathways linking environmental exposure to hematologic malignancies." (PMID 39940906, 2025).
MELTF also shares sentences with these, for which no sentence is quoted: lung carcinoma (3 papers); colorectal cancer (2); Cognitively (1); colon adenocarcinoma (1); Jaundice (1); lung adenocarcinoma (1); lung squamous cell carcinoma (1); mild cognitive impairment (1); oral cancer (1); oral cavity squamous cell carcinoma (1); osteosarcoma (1); schizophrenia (1); serous ovarian cancer (1); triple-negative breast carcinoma (1).